CALHM6 (calcium homeostasis modulator family member 6)
Description:
Pore-forming subunit of an ATP-permeable channel (By similarity). In response to pathogen-derived and proinflammatory stimuli, relocates from intracellular compartments to NK-dendritic cell and NK-macrophage immune synapses where it mediates ATP efflux and NK cell activation involved in antimicrobial and antitumor responses (By similarity). May assemble to form gap junction channel-like structures with gating and ion conductance likely regulated by membrane lipids and voltage rather than by extracellular calcium levels.
Synonyms: C6orf187; FAM26F; RP1-93H18.5; OTTHUMP00000017061; OTTHUMP00000017062; dJ93H18.5; INAM
Tractability: Antibody: UniProt places it where antibodies can reach, with high confidence; UniProt predicts a signal peptide or a membrane-spanning region; its Gene Ontology location is reachable by antibodies, with medium confidence.
Gene: Protein-coding gene on chromosome 6 (116,461,370 to 116,463,968, forward strand). Ensembl gene ENSG00000188820.
Subcellular location: Cell membrane
Gene Ontology:
Molecular function: protein binding; monoatomic cation channel activity; voltage-gated channel activity
Biological process: ATP export; monoatomic cation transmembrane transport; regulation of natural killer cell cytokine production; transmembrane transport
Cellular component: plasma membrane; immunological synapse
Genetic constraint (gnomAD): Loss-of-function variants: 15 observed, 8.05 expected, observed/expected ratio (o/e) 1.86, 90% interval 1.15 to 1.97. That is too few expected variants to judge how well the gene tolerates losing a copy. Missense variants: 434 observed, 343.12 expected, observed/expected ratio (o/e) 1.26, 90% interval 1.17 to 1.37. Synonymous variants: 212 observed, 154.28 expected, observed/expected ratio (o/e) 1.37, 90% interval 1.23 to 1.54.
Homologues: Orthologues: chimpanzee CALHM6 (98% identical), dog CALHM6 (79% identical), pig CALHM6 (78% identical), rabbit CALHM6 (75% identical), rat Calhm6 (70% identical), mouse Calhm6 (68% identical), tropical clawed frog calhm6 (46% identical), Caenorhabditis elegans clhm-1 (22% identical). Paralogues in human: CALHM5 (36% identical), CALHM4 (27% identical), CALHM2 (27% identical), CALHM1 (23% identical), CALHM3 (22% identical).
Diseases named in the same sentence as CALHM6 in open-access papers:
CALHM6 is named in the same sentence as 23 diseases in open-access papers, as found by Europe PMC text mining. Sharing a sentence is not in itself a finding about the gene and the disease. The quoted sentences say what the papers report.
Listeria monocytogenes infection (2 papers, 2023 to 2026). "Here, we generated Calhm6−/− mice and report that CALHM6 is important for the regulation of the early innate control of Listeria monocytogenes infection in vivo." (PMID 36861806, 2023).
bacterial pneumonia (1 paper, 2026). Acute infection of the lung parenchyma caused by bacteria (e.g., Streptococcus pneumoniae, Haemophilus influenzae, Chlamydia pneumoniae, Mycoplasma pneumoniae, and Legionella pneumophila). "To validate the correlation between Calhm6 and acute inflammation in humans, we found that mRNA levels of IFNG, TNFA, IL‐12, and Calhm6 in CD11b+ macrophages isolated from the peripheral blood of bacterial pneumonia patients were significantly elevated compared to healthy controls." (PMID 40999918, 2026).
co‐infection (1 paper, 2023). "Timing of CALHM6‐dependent IFN‐γ expression could be of particular relevance in controlling the magnitude of the immune response to co‐infection or in chronic inflammation." (PMID 36861806, 2023).
Graves disease (1 paper, 2025). Graves' disease is an autoimmune disorder that leads to overactivity of the thyroid gland (hyperthyroidism).It is caused by an abnormal immune system response that causes the thyroid gland to produce too much thyroid hormones. "XIST, PPP1R2C, CALHM6, AL672277.1, TSIX, SHROOM1, ADTRP, JUND, SGK1, CHKA, AO008569.1, MAP7D2, and AIF1 were down-expressed genes in TS compared with both the healthy female and the female patient with Graves’ disease." (PMID 39851522, 2025).
infection (6 papers, 2016 to 2026). The state of being infected such as from the introduction of a foreign agent such as serum, vaccine, antigenic substance or organism. "To elucidate the biology of CALHM6 and its role in infection in vivo, we generated conditional CALHM6‐deficient mice carrying a LacZ reporter allele, using embryonic stem cells from EUCOMM repository (Fig EV1A)." (PMID 36861806, 2023). "To understand why Calhm6−/− NK cells have a delayed IFN‐γ response at the early stages of infection, we first tested whether CALHM6 deficiency affected NK cell maturation." (PMID 36861806, 2023). "To address the role of CALHM6 in the immune system during infection, we focused on the intracellular pathogen Listeria monocytogenes (L. monocytogenes), a Gram‐positive bacterium that can cause serious infections in children, elderly, immunocompromised and pregnant people." (PMID 36861806, 2023). "In conclusion, M1‐and M2‐like signals synergistically regulate Calhm6 expression via Irf1 and Stat6, maintaining a balance between anti‐infection and immune tolerance signals in vivo and preventing macrophages from overly differentiating to either phenotype." (PMID 40999918, 2026). "In this study, we generated Calhm6−/− mice and showed that they fail to control L. monocytogenes burden at the peak of infection due to delayed kinetics of the innate immune response." (PMID 36861806, 2023). "We have demonstrated that CALHM6 expression is highest in macrophages, that it is transient during infection and under the tight control of pro‐ and anti‐inflammatory signals." (PMID 36861806, 2023). "By day 7 post‐infection, when the adaptive response is typically generated, both WT and Calhm6−/− achieved sterilising immunity." (PMID 36861806, 2023). "Collectively, these data suggest that CALHM6 is important at the very early stages of infection, where it affects the kinetics of NK cell activation for IFN‐γ secretion." (PMID 36861806, 2023). "In contrast, 72 h later, at the typical peak of infection, Calhm6−/− mice had a significantly higher bacterial burden in the spleen and they were generally more affected by the infection, as shown by a significantly higher weight loss." (PMID 36861806, 2023). "Collectively these findings demonstrate that Calhm6−/− mice have impaired early innate control of L. monocytogenes at the peak of infection in vivo but retain intact late control that allows them to clear bacteria after 7 days." (PMID 36861806, 2023). "The delayed kinetics of innate responses had a domino effect on the ability of Calhm6−/− mice to control bacterial burden in the early stages of infection." (PMID 36861806, 2023). "It is thought that CALHM6 regulates infection-related immunity." (PMID 37244954, 2023). "Hence, we hypothesised that CALHM6 is required for myeloid instruction of NK cell activation upon infection and that the deletion of CALHM6 would impair early innate control of L. monocytogenes." (PMID 36861806, 2023). "In support of a “delayed kinetics” hypothesis, Calhm6−/− NK cells barely produced IFN‐γ at the early stage, that is 18 h post‐infection, when compared to infected WT controls." (PMID 36861806, 2023). "In the absence of CALHM6, innate responses are delayed, impairing the innate control of infection." (PMID 36861806, 2023). "To test the “delayed kinetics” hypothesis, we injected WT and Calhm6−/− mice with L. monocytogenes i.p. and analysed NK activation, either early, 18 h post‐infection when IFN‐γ production from NK cells is at its peak in WT mice, or late, 3 days post‐infection, to detect delayed NK cell activity." (PMID 36861806, 2023). "In Calhm6−/− mice the pathogen does not initially encounter IFN‐γ‐primed macrophages and so it is not well controlled, which together with delayed inflammation makes the mice more sensitive to the infection (Synopsis figure)." (PMID 36861806, 2023).
tumor (5 papers, 2010 to 2023). "Early control of L. monocytogenes before adaptive T and B cell responses are initiated depends on NK cells, IFN‐γ and myeloid cells, the three components of the immune system previously linked to CALHM6 biology in tumour studies." (PMID 36861806, 2023). "Consequently, CALHM6 deficiency resulted in poor anti‐tumour immunity against IFN‐sensitive metastatic tumours and reduced efficacy of IFN‐dependent, poly(I:C)‐based immunotherapy." (PMID 36861806, 2023). "As innate control of L. monocytogenes depends on myeloid cells, NK cells and IFN‐γ, the three components of the immune system previously linked to CALHM6 biology in tumour studies, we tested whether CALHM6 deficiency affected early control of L. monocytogenes infection." (PMID 36861806, 2023). "CALHM6 was previously shown to play a role in NK cell activation upon recognition of tumours, and Poly(I:C) exposure." (PMID 36861806, 2023). "CALHM6, the only CALHM highly expressed in immune cells, has been linked to the induction of natural killer (NK) cell anti‐tumour activity." (PMID 36861806, 2023).
cancer (4 papers, 2016 to 2024). A tumor composed of atypical neoplastic, often pleomorphic cells that invade other tissues. "This can lead to the future possibility of CALHM6 being used as a possible therapeutic target against diseases and conditions where it is found to be dysregulated and involved such as in various cancers and infections." (PMID 38188152, 2024).
CALHM6 also shares sentences with these, for which no sentence is quoted: colitis (2 papers); AIDS (1); asthma (1); atherosclerosis (1); bacterial infection (1); breast tumors (1); Crohn disease (1); hepatitis B virus infection (1); osteoarthritis (1); parasite infections (1); primary biliary cirrhosis (1); Sepsis (1); systemic lupus erythematosus (1); Turner syndrome (1); ulcerative colitis (1); viral infection (1).